ENSG00000289571 (novel transcript)
Gene: Long non-coding RNA gene on chromosome 15 (62,173,719 to 62,210,429, reverse strand). Ensembl gene ENSG00000289571.
Gene Ontology:
Molecular function: pre-mRNA branch point binding
Biological process: mRNA branch site recognition
Cellular component: U2 snRNP